CD63 (CD63 molecule)
Diseases named in the same sentence as CD63 in open-access papers (continued):
Sharing a sentence is not in itself a finding about the gene and the disease.
infection (continued). "In addition, we have shown that treatment with CD63 siRNA post-infection, significantly inhibited virus production in supernatant, suggesting an important role for CD63 in macrophages during HIV-1 replication events occurring after proviral integration, and possibly during egress." (PMID 24507450, 2014). "Moreover, knockdown of CD63 prevented infection of HCV pseudoparticles." (PMID 23593195, 2013). "For this, we developed a CIN85 KD HEL cell line and compared CD63 exocytosis between parental and CIN85 KD cells following HSV-1(F) infection." (PMID 40990523, 2025). "For example, RNAi silencing of CD81 or CD151 reduces HCV replication, while doxycycline-induced knockdown of CD9, CD63, and CD81 increases ZIKV replication; conversely, their overexpression limits infection." (PMID 41157594, 2025). "Although Vps4 is likely required to produce CD63+ and ESCRT+ EVs during infection, this needs confirmation." (PMID 39898651, 2025). "Comparative analysis using the MACSplex EV kit revealed a significant reduction in the tetraspanins CD63, CD81 and CD9 in sEVs derived from Salmonella-infected macrophages (obtained at 24- and 48- hours post-infection) relative to uninfected controls." (PMID 40895579, 2025). "Infections were performed in hTERT-HEL cells, EVs were isolated from culture supernatants and analyzed for CD63." (PMID 40990523, 2025). "Eighteen hours after i.t. infection of BALB/c mice with Sp, we measured the relative level of the primary granule marker CD63 on the surface of pulmonary PMNs." (PMID 39120139, 2024). "Overall, during infection by herpes viruses, STING can exit the Golgi and enter in late endosomes carrying the CD63 tetraspanin." (PMID 38470056, 2024). "The RGNNV infection significantly increased the formation of exosomes, and subsequently, the expression of exosome-related proteins, including ALIX, CD63, Nedd4, and TSG101, was increased as well." (PMID 39494909, 2024). "At six days post-infection, the cells express US28, which partially co-localizes with CD63 as well as the cis-Golgi marker GM130 in a perinuclear compartment." (PMID 37575190, 2023). "The expression of exosomal markers, CD63, HSP70, and TSG101, was much lower after infection with this mutant virus." (PMID 36790212, 2023). "Compelling evidence indicates that the large extracellular loop (LEL) of mast cell-expressed TET proteins [Cluster of differentiation (CDs), such as CD9, CD63, CD81, CD82, CD151] plays a key role in the route of pathogens infection." (PMID 35310653, 2022). "By site-directed mutagenesis, we further determined that a phenylalanine at position 143 in human CD63 was the key residue for efficient membrane fusion and VSVΔG*-LUJV/GP infection." (PMID 35164564, 2022). "To determine the role of CD63 in ITGB1 internalization and virus production, we performed siRNA-mediated CD63 knockdowns and confirmed knockdown throughout infection and cell viability." (PMID 32041945, 2020). "Pre-treatment of J774.2 macrophages with GST-EC2s corresponding to CD9, CD63, and CD81 significantly suppressed MNGC formation on infection with both E264 and CDC272 strain of B. thailandensis." (PMID 32253503, 2020). "The Euclidean distances between protein aggregation profiles indicated that, while ITGB1 and collagen (COL1A1) or fibronectin (FN1) became gradually distant during infection, ITGB1 and CD63 became closer." (PMID 32041945, 2020). "Mechanistically, we show that the CD63 and CD151 C-terminal peptides decreased the disassembly of HPV16 capsids which consequently inhibited infection." (PMID 30279342, 2018). "We found that the C-terminal tails of CD63 and CD151 significantly inhibited infections of both HPV16 and HCMV." (PMID 30279342, 2018). "In summary, the C-terminal peptides of tetraspanins CD63 and CD151 showed the strongest effects on infection rates." (PMID 30279342, 2018).
infection (continued). "The LELs of CD63, CD81 and CD151 induced a minor, but significant reduction of HPV infection rates in HeLa and HaCaT cells at 24 h post infection (h.p.i.)." (PMID 30279342, 2018). "In this study, the general requirements of the tetraspanins CD9, CD63, CD81, and CD151 in infections by the most oncogenic HPV type, HPV16, were tested as previously investigated for HCMV." (PMID 30279342, 2018). "We therefore assessed the effect of BUD, FLUT, and AZI treatment on the release of CD63+/CD81+ host cell vesicles by macrophages under control conditions and upon infection." (PMID 28528362, 2017). "On the other hand, knockdown of CLDN1, TJP1, CD63, 14-3-3 β, and GLUT4 reduced HCV RNA level more than 50% at 12 hrs post infection." (PMID 23593195, 2013). "Knockdown of CD63, as well as that of the positive control CLDN1, reduced HCV RNA level more than 50% at 6 hrs post infection." (PMID 23593195, 2013). "At different duration of infection, the cells were fixed and immuno-stained using EEA1, CD63 and GM130 as markers of early endosomes, late endo(lyso)somes, and Golgi apparatus, respectively." (PMID 23382959, 2013). "The amount of CD63 co-localised with phagosomes increased at either 30 minutes (H. pylori strains NL101, NL106 and NL107), or two hours after infection (NL103 and SS1) and these maxima were maintained until the four-hour time point." (PMID 21426584, 2011). "At 40 h after infection, platelet CD63 expression was reduced relative to pre-infection, yet not different between Stk11fl/fl × Pf4-Cre and control mice." (PMID 40332331, 2025). "Although ESCRT+ EVs exert a positive effect on the infection and CD63+ EVs exert a negative effect, we found that the net effect of EVs present within the first 10 fractions of our iodixanol/sucrose gradient was overall negative for the infection." (PMID 39898651, 2025). "Similarly, it was previously shown that the treatment of cells with antibodies specific for the Tspans CD9, CD63, and CD81 reduced the infection by the coronavirus MHV and SARS-CoV, MERS-CoV, and HCoV-229E pseudovirus transductions in susceptible cells." (PMID 40872854, 2025). "CD63 exocytosis was triggered after infection with VZV and HCMV similar to HSV-1(F), but, to a lesser extent, after infection with HSV-2(G), which is consistent with our finding that STING is packaged in CD63 + EVs." (PMID 38470056, 2024). "Finally, we also present evidence that CD9/CD81/CD63+ EVs, including LC3+ EVs subset, represents a novel cell-free mechanism for dengue virus dissemination following infection of DCs." (PMID 38863700, 2024). "It is important to note that CD63 is likely not the only factor governing enhanced infection of mature and highly dense HLCs, and future research should aim to identify and confirm such other factors." (PMID 39232200, 2024). "Multiple HSV proteins are palmitoylated during infection, and the trafficking of these viral proteins through the ER to the Golgi could trigger the clustering of STING into CD63-enriched microdomains that are released in exosomes." (PMID 38470056, 2024). "Our data suggest that BM CD63+ stromal cells contribute to inflammation with Il1b expression in the absence of IL-1rn with no need of injury or infection sensing." (PMID 36596811, 2023). "Moreover, CD63, CD81 (transmembrane proteins), and HSP70 (cytosolic proteins) all showed positive results in both control and infection groups, indicating the presence of exosomes in terms of marker proteins for their general characterization." (PMID 36059498, 2022). "By multiplex bead-based flow cytometry assay, no significant increase in CD63 expression was detected between sEVs from NI or infected HIPECs upon infection, certainly due to the low proportion of positive vesicles." (PMID 36146834, 2022). "Indeed, as the CD63, CD81, and CD9 expressions in HIV-1-infected T cells were enhanced for up to 24 h post infection, infectious exosomes displayed higher CD81 and CD9." (PMID 34769038, 2021).
infection (continued). "The lack of an effect of anti-CD63 antibodies on infection-induced MNGC formation in J774.2 macrophages is perhaps unsurprising given the very low levels of this antigen on the surface of these cells." (PMID 32253503, 2020). "As expected, infection of untreated neutrophils with Y. pestis ΔyopEH triggered significant primary granule release (high CD63 MFI), while infection with the Y. pestis wild-type strain inhibited primary granule release from neutrophils (low CD63 MFI)." (PMID 31822588, 2019). "There was a slight increase in CD63 levels in RSV vs mock exosomes, which was however statistically significant, suggesting that infection could enhance exosome release." (PMID 29321591, 2018). "To investigate whether CD63 plays a role in HPV infection, we performed a series of infection assays using various keratinocyte cell models depleted of CD63." (PMID 27578500, 2016). "There was no change in CD31, CD66b and CD63 expression on blood neutrophils post-infection, consistent with their role in endothelial transmigration and as neutrophil activation markers respectively." (PMID 23834268, 2013). "In the absence of infection, reactivity with anti-CD63 antibody and weak signal from EEIA-expressing early endosomal structures showed neuronal TLR3 to be confined to the endosomal compartment, associated mainly to the late endosomes and multivesicular bodies." (PMID 19247444, 2009). "Antibodies against CD63 had a strong inhibitory effect in 293TT cells (42±13% inhibition) but showed no reduction of infection in HeLa cells." (PMID 18836553, 2008). "However, as seen with CD63, we detected increasing colocalization of HPV16 particles with CD151 on the cell surface as the infection process proceeded." (PMID 18836553, 2008). "Additionally, immunofluorescence experiments were performed with CD63 (a late endosome marker) antibodies, together with TGN46 and showcased that upon infection, BST2 is downregulated and mainly present in TGN46 positive compartments while less present in CD63 compartments." (PMID 39561185, 2024). "CD63 is a tetraspanin family glycoprotein along with CD29 (integrin β1), CD44 (a multifunctional transmembrane receptor) (respectively), and LAMP (also known as CD107b), which were also found to be expressed and hence packaged within control and infection EVs derived from CCoV-infected CRFK cells." (PMID 36979955, 2023). "Moreover, the inability of Flag-C99 to affect infection was unsurprising given that it did not affect Gag localization to MVBs or CD63-positive vesicles, in line with ubiquitination of C99 supporting exocytic vesicle trafficking and C99 degradation." (PMID 37454116, 2023). "Our results suggest that CD63 may similarly promote ITGB1 internalization during infection, but this was not previously demonstrated." (PMID 32041945, 2020). "However, the ability of the CD63+ve exosomes derived from HIV-1 infected T cells to transfer infection to fresh T cells ranged from no to minimal infection." (PMID 29093555, 2017). "The blots revealed that CD63 is enriched in all EVs, regardless of infection by the pathogen." (PMID 28464853, 2017). "Pigs from groups CD42, CD56 and CD63 showed no sign of infection until slaughter (28 days after contact) either at necropsy, or from analysis of weekly blood samples or nasal swabs, which indicated that the inoculated pigs were no longer infectious at least from 42 dpi." (PMID 23061672, 2012). "There was little or no co-localisation of CD63 with phagosomes immediately after infection." (PMID 21426584, 2011). "Thus, the ppsE mutation drove a significant percentage of H37Rv cells toward a compartment that transiently accumulated LysoTracker in the first few hours after infection without fusion with CD63 positive-lysosomes." (PMID 19197369, 2009).
infection (continued). "While C83 does not inhibit infection, blocking C99 degradation using ubiquitin-site mutants or preventing its further processing into toxic β-amyloids using a γ-secretase inhibitor impairs Gag entry into CD63-positive MVBs and suppresses the release of infectious viral particles." (PMID 37454116, 2023). "These exosomes have minimal capacity for infection in recipient cells leading us to believe that genomic RNAs that may be packages in the exosomes (CD63 positive exosomes) are not infectious primarily due to lack of all the components necessary for the reverse transcription step." (PMID 26539170, 2015). "Although these data support the existence of the A‐H subsets, when analyzed across all time points following infection, astrocytes clustered into eight unbiased subsets not defined by CD71/Tfrc, CD51/Itgav, or Cd63 expression." (PMID 40635167, 2025). "We also showed an increase of ubiquitinated BST2 during infection and a decrease of BST2 presence in CD63 compartments compared to non-infected cells." (PMID 39561185, 2024). "All three tetraspanins—CD9, CD63, and CD81—were present in BEVs irrespective of infection or treatment status." (PMID 33036231, 2020). "A recent paper showed that HSV-1 triggered the release of CD63 positive EVs but not alter the exocytosis of TSG101 or Alix, suggesting the infection triggers ESCRT-independent pathways for the release of EVs." (PMID 31068945, 2019). "Expression of CD31, CD63 and CD66 on blood neutrophils did not change after infection in either group (data not shown)." (PMID 23834268, 2013). "Importantly, siRNA-mediated knockdown of TJP1, CD63, 14-3-3 β, SUMO1 or GLUT4 reduced the infectivity of HCV by more than 50%, whereas knocking down either of the other two proteins (integrin β1 and CASK) did not affect infection of HCV JFH1 5A-Rluc." (PMID 23593195, 2013). "Furthermore, flow cytometry experiments demonstrated that depletion of CD63 had no apparent effect on internalisation of HPV16: staining intensity of polyclonal anti-L1 antibody K75, which detects surface bound PsV, was comparable in control and CD63-depleted cells 24 hours after infection." (PMID 27578500, 2016).
adenocarcinoma (4 papers, 2020 to 2023). A common cancer characterized by the presence of malignant glandular cells. "(E–E’’) CD63 and β-catenin were stabilized in adenocarcinoma I, and moderate colocalization was found between CD63 and β-catenin." (PMID 37902809, 2023). "(F–F’) CD63 and β-catenin were strongly stabilized and colocalized in adenocarcinoma stage IV CRC." (PMID 37902809, 2023).
bacterial infection (2 papers, 2018 to 2024). "We speculate that CD63 also plays an important role in bacterial infection in C. idella." (PMID 30424518, 2018).
colorectal (2 papers, 2014 to 2016). "However, CD63 was only found in apical EVs from colorectal cancer cells." (PMID 27721471, 2016).
immune dysfunction (2 papers, 2011 to 2025). "This IL-1R2+ Monocytes subset exhibits hallmarks of immune dysfunction, including low expression of HLA-DR and high levels of macrophage markers (MS4A4A, CD63) and immune checkpoints." (PMID 41293423, 2025).
hematologic cancer (1 paper, 2022). "To challenge the delivery of siRNAs into hematologic cancer cells, we developed exosome-capturing anti-CD63 mAb-conjugated small interfering RNAs (siRNA) with branched Arg linkers (9+9mer)." (PMID 35158834, 2022).
CD63 also shares sentences with these, for which no sentence is quoted: acute myeloid leukemia (4 papers); allergic rhinitis (4); Alzheimer disease (3); head and neck cancer (3); rectal cancer (3); Airway obstruction (2); brain tumor (2); Erythema (2); injury (2); lupus (2); metastatic carcinoma (2); nasopharyngeal carcinoma (2); neurologic disease (2); uveal melanoma (2); acute lymphoid leukemia (1); autoimmune disease (1); autoimmune thrombocytopenia (1); bacterial pneumonia (1); basal cell carcinoma (1); benign granular cell tumor (1); benign ovarian tumors (1); bleeding disorders (1); breast ductal carcinomas (1); Breast Invasive Carcinoma (1); carcinosarcoma (1); cardiac disease (1); cervical intraepithelial neoplasms (1); Chagas disease (1); cholangiocarcinoma (1); chondrosarcoma (1).
A further 71 diseases each share a sentence with CD63 in 1 paper.